RN7SL786P (RNA, 7SL, cytoplasmic 786, pseudogene)
Gene: Miscellaneous RNA gene on chromosome 11 (75,742,129 to 75,742,426, forward strand). Ensembl gene ENSG00000263993.
Homologues: Orthologues: chimpanzee Metazoa_SRP (99% identical), macaque Metazoa_SRP (94% identical). Paralogues in human: RN7SL1 (85% identical), RN7SL2 (85% identical), RN7SL3 (84% identical), RN7SL47P (84% identical), RN7SL126P (83% identical), RN7SL664P (83% identical), Metazoa_SRP (83% identical), RN7SL627P (83% identical), RN7SL357P (83% identical), RN7SL620P (83% identical), RN7SL709P (82% identical), RN7SL479P (82% identical), and 699 more.